NRP1 (neuropilin 1)
Diseases named in the same sentence as NRP1 in open-access papers (continued):
Sharing a sentence is not in itself a finding about the gene and the disease.
tumor (continued). "This NRP1 downregulation exists in heterotopic tumor but is less evident in intracerebral tumors probably to specific mechanisms of NRP1 regulation not yet elucidated." (PMID 36457009, 2022). "Growing evidence implicates a role for neuropilin-1 in promoting cancer progression by acting as a co-receptor for molecules involved in the EMT pathway and metastasis in tumor tissue such as vascular endothelial growth factor, placental growth factor, and TGF-β1." (PMID 35303925, 2022). "Biodistribution studies of antibodies against the VEGF receptor NRP1 have concluded that saturation of non-tumor sinks was required to improve tumor exposure to the compound of interest." (PMID 35203573, 2022). "We demonstrate that the endothelial-specific cotargeting of both NRP receptors, NRP1 and NRP2, provides effective inhibition against tumor growth and secondary site metastasis in multiple cancer models, likely by potentiating the rapid delivery of VEGFR-2 to late-endosomes for degradation." (PMID 36970722, 2022). "Furthermore, Tr1 cells share the expression of suppressive molecules, such as Nrp-1, PD-1, and CD73, which are highly expressed on Tr1 cells found in tumor-infiltrating leukocytes (TILs)." (PMID 35860556, 2022). "Nrp1 is essential for immune response and identified as the co-receptor of VEGF to mediate angiogenesis, and Nrp2 exerts a significant role in VEGF-C/D/VEGFR-3-mediated tumor lymphangiogenesis and lymphatic metastasis." (PMID 35155237, 2022). "Neuropilin-1 (NRP1) is a transmembrane or cytosolic protein that acts on several signaling pathways, such as angiogenesis through VEGF and HGF in endothelial cells, and is a tumor promotor overexpressed in several tumor tissues." (PMID 35887311, 2022). "Utilizing these models, we demonstrate that in multiple models of cancer, cotargeting the endothelial expression of both NRP1 and NRP2 severely inhibits primary and secondary tumor growth and angiogenesis, to a much greater extent than when either NRP receptor is targeted alone." (PMID 36970722, 2022). "While tumor angiogenesis was still observed in Nrp1 knockout models, there was a lack of VEGF-mediated proliferation and no increase in CD34+ CSC population." (PMID 36203599, 2022). "In contrast, the frequency of Neuropilin-1+ (NRP1) Helios+ Tregs was not significantly increased within the tumor compared to DLN in either obese or lean mice." (PMID 35472214, 2022). "In addition, we also analyzed tumor angiogenesis genes, and the results showed that seven tumor angiogenesis genes (HIF1A, PDGFB, NRP1, VEGFB, FGFR1, ROBO1, and SLIT1) had substantially higher expression in the high-risk group compared with the low-risk group." (PMID 35311113, 2022). "Many reports also indicate that NRP-1, which is found on many types of cancer cells, lacks catalytic activity and may also serve as a separate receptor for VEGF-A165, stimulating tumor growth and metastasis." (PMID 35056995, 2022). "The group further showed that the vessel area in the tumor, vessel perfusion, vessel branching points, and vessel density were decreased when macrophages lacked Nrp1." (PMID 36203599, 2022). "As both NRP1 and NRP2 have been reported to regulate FN fibrillogenesis in ECs in the past, we considered whether the deposition of EDA-FN around tumor vessels would be perturbed in our knockout models." (PMID 36970722, 2022). "It is also important to note that EG00229 exhibited minimal effects on parental cells, but in cells that exhibited acquired resistance to targeted therapies, Nrp1 knock down and EG00229 treatment were sufficient to resensitize tumor cells to the targeted therapies." (PMID 36203599, 2022). "When tumor cells are in low oxygen and low pH, they will release Neuropilin-1 (Nrp-1), TGF-β, IL6, IL4, Tim-3 to promote the transformation of macrophages into M2 type, which can help tumor cells to escape immune and secrete growth factors to enhance tumor growth." (PMID 36684237, 2022).
tumor (continued). "In addition, due to the overexpression of neuropilin-1 (NRP-1) on angiogenic endothelial cells, it is usually regarded as a common target of tumor vasculature-targeted therapy." (PMID 35910806, 2022). "Moreover, heterogeneity removal showed a significant correlation of NRP1 overexpression not only with OS, but also with PFS and tumor pathogenesis." (PMID 35884516, 2022). "Interestingly, recent studies have shown that integrins and neuropilin-1 may also act as important receptors for CgA, vasostatin-1, CgA1-373, and other fragments, in endothelial cell biology, cardiovascular function, angiogenesis, wound healing, and tumor growth." (PMID 36559048, 2022). "Neuropilins (NRP-1, 2) as the multifunctional non-tyrosine kinase receptors are expressed in tumor cells supporting angiogenesis and tumor growth." (PMID 36146510, 2022). "NRP1flflNRP2flfl.ECKO PyMT-BO1 tumors were found to be approximately 70% less vascularized than respective Cre-negative control tumors, corroborating our CMT19T studies, and confirming that the expression of NRP1 and NRP2 is essential for tumor angiogenesis in multiple cancer models." (PMID 36970722, 2022). "NRP-1, a transmembrane glycoprotein, is a co-receptor for members of the vascular endothelial growth factor (VEGF) family, expressed on neovascular endothelial cells, and plays an important role in promoting tumor angiogenesis." (PMID 36497021, 2022). "Knocking out NRP‐1, an important T cell surface molecule, or reducing CARMA1 expression in Treg cells to destroy the CARMA1‐BCL10‐MALT1 (CBM) complex effectively promoted IFN‐γ secretion by Treg cells and led to an effective anti‐tumor response." (PMID 34658167, 2021). "Thus, IFNγ released by Nrp1−/− Tregs results in increased fragility of other populations of intratumoral Tregs, increasing anti-PD1-driven anti-tumor immune responses." (PMID 33801234, 2021). "This peptide binds to the αVβ3 and αVβ5 integrins and to neuropilin-1 (NRP1) receptors increasing the pore diameter and surface area of blood vessels in the tumor, reducing the influence of pressure in its interstitium, and, in consequence, increasing the diffusion rate of small molecule drugs." (PMID 33445797, 2021). "Therefore, we tested the 1E9 antibodies on ccRCC (A498 and 786-O, high expression of Neuropilin 1 and Neuropilin 2) and breast (MDA-MB-231, high expression of Neuropilin 1 positive and low expression of Neuropilin 2) tumor cells." (PMID 34067671, 2021). "Our data thus far have demonstrated that the absence of PLEXIND1 inhibits tumor growth and PLEXIND1 downregulation in PANC-1 cells causes an increase in NRP1 protein expression." (PMID 34439202, 2021). "Furthermore, there are reports of VEGF-mediated signaling having direct, autocrine effects by promoting tumor cell survival, and contributing to tumor invasiveness by carcinoma cells expressing VEGFR-1, VEGFR-2, and neuropilin 1 (NRP1)." (PMID 34298750, 2021). "Our present study showed that in IR cells, NRP-1 plays a role in enhancing tumor motility, but not angiogenesis." (PMID 34698100, 2021). "Our current data based on cultured 3D spheroids and β5 integrin KO tumors in mice strongly suggest that, in the extravascular tumor tissue, the expression of β5 integrin rather than NRP-1 is critical for successful iRGD penetration." (PMID 33750829, 2021). "First, NRP1, by acting as a VEGF co-receptor, will guide the LTreg within the tumor." (PMID 34277411, 2021). "Analysis of NRP-1 expression levels in comparison to internalization of iRGD-IP, LinTT1-IP and TT1-IP, or RPARPAR-IP found that samples with the highest receptor expression also had high tumor aggressiveness scores and showed prominent TPP-IP internalization." (PMID 34683924, 2021). "In addition, NRP1, which functions as a co-receptor of VEGF and VEGF receptor, can also motivate tumor angiogenesis." (PMID 34721048, 2021).
tumor (continued). "Disruption of the CBM signalosome complex or targeting Helios or Nrp1 or ligation of GITR in Tregs is shown to be effective for tumor control without peripheral autoimmune effects reported." (PMID 34394124, 2021). "NRP1 regulates GBM growth and invasion by balancing tumor cell responses to VEGF-A and TGF-β." (PMID 34277411, 2021). "D-MVD also decreased in the tumour xenografts that overexpressed miR-590; D-MVD was partially restored to the normal level after overexpressing VEGFR1/2 or NRP1, and D-MVD was completely restored to the normal level after overexpressing both VEGFR1/2 and NRP1." (PMID 32303680, 2020). "Several strategies have been studied in preclinical tumor models to interfere with NRP-1 in the TME, ranging from genetic strategies, such as modification of cancer cells to express soluble NRP-1 or downregulate NRP-1, to the use of mAbs that block NRP-1." (PMID 33266104, 2020). "Thus, this systematic analysis provides evidence suggesting the potential use of NRP1 as an effective biomarker for patient survival in STAD and a therapeutic target modulating the tumor immune microenvironment." (PMID 32408477, 2020). "Conversely, RGD peptides only bind to integrins, but not to NRP-1, and are thus accumulated only inside and/or around tumor vessels." (PMID 32847045, 2020). "A semiquantitative analysis of PlGF, VEGFR-1, NRP-1, and NRP-2 levels in this tumor, performed by immunohistochemistry on tumor specimens from patients undergoing extrapleural pneumonectomy, showed that the four factors were specifically overexpressed in mesothelioma." (PMID 32085654, 2020). "Nevertheless, we also note that integrin activation appeared as a universal mechanism detected in pre-activation cells of tumor core and periphery, while CD44 and NRP1/2 activity was higher in tumor core and chemokine receptors CCR1 and CSF1R were higher ranked in the tumor periphery." (PMID 33177572, 2020). "After interacting with the tumor vascular endothelium integrins, iRGD undergoes proteolytic cleavage followed by the formation at C-terminus of a truncated CRGDK/R peptide that binds to neuropilin-1 and the activates transport pathway inside the tumor stroma." (PMID 33050526, 2020). "The pattern of VEGFR2 and NRP1 expression in RCC, that is, VEGFR2 in the endothelial cells and NRP1 in both endothelial and tumor cells, indicated that VEGFR2/NRP1 complexes could form both in trans and cis configurations." (PMID 31880322, 2020). "In tumor tissue PL3-NWs were found in the areas positive for TNC-C and NRP-1 immunoreactivities." (PMID 32242067, 2020). "Since the epithelial-to-mesenchymal transition (EMT) is an important mechanism of tumour invasion and metastasis and VEGFR1/2 and NRP1 can promote the occurrence of EMT, we speculated that miR-590 can regulate the occurrence of EMT." (PMID 32303680, 2020). "However, a high proportion of intratumoural Nrp1−/− Tregs produced IFN-γ, driving the fragility of surrounding wild-type Tregs, boosting antitumour immunity, and facilitating tumour clearance, which is required for the response to anti-PD-1." (PMID 32680511, 2020). "Furthermore, systemic administration of antibodies against the binding site of CgA1-373 for neuropilin-1 (PGPQLR), an important receptor for its pro-angiogenic activity, significantly reduced Panc02-tumor growth." (PMID 33425767, 2020). "Moreover, interactions related to tumor angiogenesis, such as NRP1-VEGFB, ADRB2-VEGFB, and NRP1-VEGFA were extensively recovered in tumor, implying their potential roles in promoting tumor angiogenesis." (PMID 33298893, 2020). "In most cancers, the co-expression of NRP1 and NRP2 stimulates tumor growth and invasiveness." (PMID 32766254, 2020). "Neuropilin-1 (NRP-1), the major co-receptor of vascular endothelial growth factor receptor-2 (VEGFR-2), may also independently act with VEGF-A165 to stimulate tumour growth and metastasis." (PMID 33374715, 2020).
tumor (continued). "Moreover, samples with VEGFR2/NRP1 trans complexes, detected by PLA, or alternatively, NRP1 expression on perivascular or tumor cells, detected by IF staining, exhibited decreased overall vessel area and reduced vessel size." (PMID 31880322, 2020). "Similarly, the peptide A7R (ATWLPPR) specifically binds to NRP1, has anti-angiogenic activity in vitro by inhibiting NRP1/VEGFR2 signaling, and curbs tumor angiogenesis and tumor growth in vivo." (PMID 30717262, 2019). "Hypoxic tumor cells enhance Treg recruitment, through the production of CCL28 which interacts with CXCR10 (a proangiogenic and immunosuppressive molecule), the expression of neuropilin-1 (NP-1) which attracts Tregs in response to VEGF, or the secretion of the chemoattractant TGF-β by tumor cells." (PMID 30708988, 2019). "The interaction between the extracellular domain of NRP1 and epidermal growth factor receptor (EGF) leads to the stimulation of tumor cells’ response to EGF and transforming growth factor-α (TGF-α), which may contribute to EGFR activation." (PMID 30871059, 2019). "In our experiments, we found that NRP1 could effectively inhibit the secretion of MCP1 and RANTES in the tumor migratory microenvironment, after irradiation, the secretion of MCP1 and RANTES showed a further decrease." (PMID 31417646, 2019). "Native Cltx with amidated arginine at its C-terminus did not bind NRP1 but acted as a cryptic peptide; its metabolism to peptides bearing a free C-terminal arginine and the capacity to bind NRP1 took place in the tumor microenvironment." (PMID 31208428, 2019). "Overall, a reasonable interaction was observed, with positive correlation between NRP1 expression in tumor lysate and ER-472 therapeutic window noted for 11 of the 13 total models." (PMID 31208428, 2019). "Recently, semaphorin 4a (Sema4A) was described as a novel NRP1 ligand critically involved in suppression of anti-tumor responses by mTregs, but additional ligands mediating immune-modulatory effects of NRP1 are not well-defined." (PMID 31572401, 2019). "Deamidation occurs in tumor and the resultant Cltx-COOH and several derived peptides bind to NRP1." (PMID 31208428, 2019). "NRP-1 enhances the binding of VEGF-A and intensifies VEGF-induced tumor angiogenesis." (PMID 31839752, 2019). "Thus, in this context, NRP1 interference was found to inhibit TAM function, promote anti-tumor immune response and inhibit cancer growth and metastatic progression." (PMID 31027288, 2019). "Blocking NRP1 with antibodies selectively inhibits angiogenesis and in combination with anti-VEGF therapy, it further reduces tumor growth, suggesting that NRP1 antibodies may render tumor vessels more responsive to anti-VEGF therapy." (PMID 30717262, 2019). "It has been reported that the delivery of NRP1 via exosomes/sEVs from MDCK oncogenic cells to the surface of recipient endothelial cells leads to increased responsiveness to soluble angiogenic ligands such as VEGF-A, thereby activating tumor angiogenesis." (PMID 31852509, 2019). "PC-3 tumor lysates had high NRP1 mRNA and protein expression and a wide ER-472 therapeutic window, versus minimal or no NRP1 detected in the MIA PaCa-2 and BxPC-3 tumor models where ER-472 was less effective." (PMID 31208428, 2019). "Interestingly, when the iRGD peptide is cleaved by proteases in tumor cells, it produces a CRGDK/R derivative peptide that has diminished affinity for αv integrin but increased affinity for neuropilin-1 (NRP-1)." (PMID 31072061, 2019). "As in the previous study, significantly higher antitumor activity was observed for ER-472 in the NRP1 WT versus KO model, while ER-271 was equipotent regardless of NRP1 status, with tumor regression observed in both models." (PMID 31208428, 2019). "In this way, NRP1 on non-ECs can inhibit angiogenesis and reduce the initiation of tumor growth by altering VEGFR2 internalization and signaling." (PMID 30717262, 2019).
tumor (continued). "In metastatic cervical cancer, Nrp-1 expression on Treg in the tumor draining lymph node (TdLNs) is far higher than without metastatic implants." (PMID 31681327, 2019). "The concentrations of Nrp1 and Nrp2 in 43 of the tumor patient samples were within the ranges of those found in normal human serum." (PMID 30758083, 2019). "In addition to integrin αVβ3, neuropilin-1 (NRP-1) is a functional regulator that interacts with the vascular endothelial growth factor (VEGF) receptor and is particularly expressed in tumor angiogenic vessels." (PMID 31394799, 2019). "NRP1 is generally considered as a tumor-promoting coreceptor, but the situation is not entirely clear." (PMID 30717262, 2019). "Strikingly however, this results in a tumour-specific disaggregation of tumour blood vessels, in which tumour cells with their non-polarized cell expression of neuropilin-1 have integrated into the endothelial cell lining." (PMID 30823637, 2019). "BDCA-4 is identical to neuropilin-1 (NP-1), a receptor known to be expressed on other non-hematopoietic cells, such as neurons and some tumor cells." (PMID 30987228, 2019). "NRP1 is essential for VGFA-triggered and angiogenesis-inducing signaling in ECs and in tumor cells." (PMID 30717262, 2019). "This distinction implies that the NRP1 present on human PC-3 tumor cells rather than in mouse vasculature is relevant for the more potent antitumor effect of ER-472 in this model." (PMID 31208428, 2019). "Later in ontogeny, NRP1 is expressed on arterial ECs and in the tumor vasculature, but not on venous or lymphatic ECs." (PMID 30717262, 2019). "Since then we also verified this result in tumor-bearing tissues, and we found that after ionizing radiation, the number of fibroblasts transformed into CAF cells increased and was positively correlated with NRP1 expression." (PMID 31417646, 2019). "LinTT1 is processed by tumor-derived proteases, such as uPA, to C-terminally expose the C-end rule motif of the peptide (i.e. AKRGAR), which is capable of interacting with the cell- and tissue-penetration receptor NRP-1." (PMID 29721153, 2018). "Our lab has demonstrated that Treg-restricted deletion of cell surface protein Neuropilin (Nrp1, CD304) results in substantially reduced tumor growth with no autoimmune defects." (PMID 30400822, 2018). "Additionally, in a murine xenograft model, it has been shown that a small peptide inhibitor that disrupts the oligomerization of Nrp1 and PlexinA1 reduces GBM proliferative potential and tumor angiogenesis in vivo." (PMID 32914058, 2018). "In addition, NRP-1 also binds the RTK c-Met, leading to increased proliferation, survival and migration of tumor cells in human glioma and pancreatic cancer." (PMID 29396568, 2018). "The intensity of the NRP1 signal was scored in blood vessels, in tumor cells or both, based on a graded scale from no to weak and moderate intensity." (PMID 30027561, 2018). "For instance, this study showed that Sema3A binding NRP-1 can increase vascular permeability without an inhibition of tumor growth." (PMID 30598022, 2018). "The position of PLA signals in this condition was compared with fibrosarcomas lacking NRP1 expression in tumor cells, negating the formation of trans‐complexes." (PMID 30027561, 2018). "As shown for some of the semaphorins, these proteins can compete with VEGF due to its interaction with neuropilin receptors (NRP1 and NRP2), which leads to inhibition of endothelial cell migration, proliferation, and capillary structures formation of the tumor." (PMID 30304095, 2018). "Moreover, only GAC and PDAC showed expression of NRP1 in tumor cells in close proximity to blood vessels, potentially allowing the formation of VEGFR2/NRP1 complexes in cis and/or trans." (PMID 30027561, 2018). "Hence, our results show that TGFβ can downregulate NRP1 expression in KRASmt cells (PANC-1, A549) thereby contributing to tumor growth in our model." (PMID 29018205, 2017).